DNM3 (dynamin 3)
Diseases named in the same sentence as DNM3 in open-access papers:
DNM3 is named in the same sentence as 41 diseases in open-access papers, as found by Europe PMC text mining. Sharing a sentence is not in itself a finding about the gene and the disease. The quoted sentences say what the papers report.
hepatocellular carcinoma (9 papers, 2017 to 2024). A malignant tumor that arises from hepatocytes. "Interestingly, dynamin 3 gene (DNM3) was identified as one of the genes associated with hepatocellular carcinoma pathogenesisis, from a triple combination array carried out in surgical specimens obtained from hepatocellular carcinoma (HCC) patients." (PMID 28402939, 2017). "For example, in hepatocellular carcinoma, the downregulation of DNM3 promoted cell proliferation by increasing cell cycle-associated proteins, including cyclin D1, and the upregulation of DNM3 induced cell apoptosis and inhibited tumor growth." (PMID 38742190, 2024). "Recently, Inokawa and colleagues reported the decreased expression of dynamin-3 in hepatocellular carcinoma tissue." (PMID 37445659, 2023). "DNM3 has been shown to play a tumor-suppressive role in cervical cancer, colon cancer, lung cancer, and hepatocellular carcinoma." (PMID 36528667, 2022). "Dynamin 3 serves as a tumor suppressor in hepatocellular carcinoma pathogenesisis and its expression is decreased during the disease condition due to gene hypermethylation." (PMID 28402939, 2017). "DNM3 (Dynamin 3), involved in exosomes, endocytosis, and tumor metastasis, is considered as a tumor suppressor gene in a variety of cancers such as non-small-cell lung cancer (NSCLC), hepatocellular carcinoma, papillary thyroid carcinoma, and colon cancer." (PMID 38962012, 2024).
cervical cancer (4 papers, 2022 to 2023). A primary or metastatic malignant neoplasm involving the cervix. "The low expression of DNM3 was significantly associated with high pathological grading of cervical cancer." (PMID 35631574, 2022). "MiR-214, located in the DNM3 gene on q24 and q3 of human chromosome 1, was first discovered in the process of HeLa cell apoptosis in cervical cancer and is reported to be closely related to cell growth, migration and invasion." (PMID 37305554, 2023). "Jing Fa found that DNM3 overexpression could inhibit the proliferation, migration, and invasion of cervical cancer cells." (PMID 35936781, 2022).
papillary thyroid carcinoma (3 papers, 2021 to 2024). "Further, linc01278 is known to sponge miR-376c-3p to positively regulate the DNM3 expression and ultimately acting as a tumor suppressor gene in papillary thyroid carcinoma." (PMID 35913967, 2022). "Our previous study shows that LINC01278 inhibits the malignant proliferation and invasion of papillary thyroid carcinoma (PTC) cells by regulating the miR-376c-3p/DNM3 axis." (PMID 34273985, 2021).
breast carcinoma (2 papers, 2021 to 2022). "As expected, methylation levels of ADCY4, CPXM1, DNM3, GNG4, MAST1, PRDM14, and ZNF177 were found to be increased in breast cancer, and all with p values lower than 0.001." (PMID 33499882, 2021). "To further explore the clinical value of these biomarkers, we evaluated whether 6 of our differentially methylated genes—ADCY4, CPXM1, DNM3, PRDM14, PRKCB, and ZNF177—had any relation with overall survival of breast cancer patients." (PMID 33499882, 2021). "Methylation pattern of MAST1, PRDM14, and ZNF177 may represent new diagnostic biomarkers for breast cancer, while methylation of ADCY4, CPXM1, DNM3, PRDM14, PRKCB, and ZNF177 may hold prognostic potential for breast cancer." (PMID 33499882, 2021). "Moreover, we showed that DNA methylation landscape of ADCY4, CPXM1, DNM3, PRDM14, PRKCB, and ZNF177 could be selected as accurate biomarkers for the prognosis of breast cancer." (PMID 33499882, 2021).
colorectal cancer (2 papers, 2022). A primary or metastatic malignant neoplasm that affects the colon or rectum. "Cheng and his colleagues found that the expression level of the DNM3 gene in colorectal cancer was significantly correlated with tumor size and clinical case type." (PMID 35936781, 2022).
glioblastoma (2 papers, 2020 to 2022). The most malignant astrocytic tumor (WHO grade IV).
glioma (2 papers, 2024 to 2025). A benign or malignant brain and spinal cord tumor that arises from glial cells (astrocytes, oligodendrocytes, ependymal cells). "In glioma, exosomal miR-221 induces temozolomide resistance by targeting DNM3, which normally suppresses DNA repair." (PMID 41369385, 2025). "Additionally, exosomal miR-221 targets dynamin 3 (DNM3) to induce glioma progression and temozolomide resistance, further supporting its utility as a liquid biopsy marker." (PMID 41369385, 2025). "Yang and colleagues revealed that sEVs-miR-221 induced TMZ resistance in glioma via targeting DNM3." (PMID 38951882, 2024).
Parkinson disease (2 papers, 2021 to 2023). A progressive degenerative disorder of the central nervous system characterized by loss of dopamine producing neurons in the substantia nigra and the presence of Lewy bodies in the substantia nigra and locus coeruleus. "DNM3 may be a useful target for the therapy of age-related neurodegenerative diseases, as studies have revealed that genetic variability in DNM3 alters the age of onset for LRRK2 Gly2019Ser Parkinsonism and informs disease-relevant translational neuroscience." (PMID 37666846, 2023).
schizophrenia (2 papers, 2015 to 2022). A major psychotic disorder characterized by abnormalities in the perception or expression of reality. "Additional proteins with schizophrenia rare variant associations (via the SCHEMA consortium) altered in 22q11.2del neurons included DNM3, MAGI2 and TRIO (downregulated in patient neurons) and HIST1H1E, SRRM2 and ZMYM2 (upregulated in patient neurons)." (PMID 35760976, 2022). "DNM3 in the candidate region of 1q24.3 is disruptively mutated in some of schizophrenia patients." (PMID 26136833, 2015). "In the candidate CNV regions, 26 regions had no overlaps with the common CNVs found in Asian populations and included the genes (i.e., ANTXRL, CHST9, DNM3, NDST3, SDK1, STRC, SKY) that are associated with schizophrenia and/or other psychiatric diseases." (PMID 26136833, 2015).
Sézary syndrome (2 papers, 2022 to 2023). "In addition, DNM3 is also upregulated in T-cell lymphoma (Sézary syndrome) originating from the skin." (PMID 36670743, 2023).
Alport syndrome (1 paper, 2021). A rare renal disease characterized by glomerular nephropathy with hematuria progressing to end-stage renal disease (ESRD), frequently associated with sensorineural deafness, and occasionally with ocular anomalies. "Osteopontin gene deletion reduces renal expression of dynamin-3 and LDL receptor and lowers blood pressure in Alport syndrome mice." (PMID 33574248, 2021).
atopic dermatitis (1 paper, 2020). "The shared expression of DNM3 in SS and L-HES is surprising because DNM3 is a component of two multi-gene panels that differentiated SS from MF and BID cases including psoriasis, atopic dermatitis, and benign erythroderma with sensitivity and specificity over 95%." (PMID 32872487, 2020).
central obesity (1 paper, 2024). "Studies have identified several genes associated with central obesity and IFG, including ADAMTS9, TBX15-WARS2, and DNM3-PIGC." (PMID 38917085, 2024).
cholangiocarcinoma (1 paper, 2022). A carcinoma that arises from the intrahepatic biliary tree (intrahepatic cholangiocarcinoma) or from the junction, or adjacent to the junction, of the right and left hepatic ducts (hilar cholangiocarcinoma). "The DNM3 protein level in eight pairs of cholangiocarcinoma tissues was detected by Western blots, indicating that DNM3 was down-regulated." (PMID 35200104, 2022). "Collectively, our findings firstly pointed out that exosomal miR-23a-3p was conducive to the progression of cholangiocarcinoma by interaction with DNM3, which provided potential evidence for cancer treatment." (PMID 35200104, 2022). "QRT-PCR showed DNM3 mRNA was downregulated in 60 pairs of cholangiocarcinoma tissues and normal tissues." (PMID 35200104, 2022). "Furthermore, we found Dynamin3 (abbreviated as DNM3) turned out to be a target of miR-23a-3p, while DNM3 was down-regulated in cholangiocarcinoma." (PMID 35200104, 2022). "Collectively, our findings firstly pointed out that exosomal miR-23a-3p was conducive to the progression of CCA by interaction with DNM3, miR-23a-3p might be a new biomarker for cholangiocarcinoma treatment." (PMID 35200104, 2022).
endometriosis (1 paper, 2024). The growth of functional endometrial tissue in anatomic sites outside the uterine body. "The expression of SYNE1 and DNM3 were significantly decreased in endometrium of both endometriosis and PCOS compared to control subjects." (PMID 38742190, 2024). "Microarray and RNA-seq verified the expressions of SYNE1 and DNM3 were significantly altered in the endometrium of patients with endometriosis or PCOS compared to those of control subjects." (PMID 38742190, 2024). "SYNE1 and DNM3 were potential shared genes between endometriosis and PCOS." (PMID 38742190, 2024). "In addition, microarray dataset and RNA sequencing dataset indicated the mRNA expressions of SYNE1 and DNM3 were downregulated in endometrium of patients with endometriosis or PCOS compared with control groups." (PMID 38742190, 2024).
glaucoma (1 paper, 2016). Increased pressure in the eyeball due to obstruction of the outflow of aqueous humor. "For the rs481154‐rs11154524 interaction, both SNP‐associated genes, SAMD3 and DNM3, again have known glaucoma associations." (PMID 27386793, 2016).
growth deficiency (1 paper, 2019). "Moreover, they proposed that deletions of two of the genes within the SRO, namely, the dynamin 3 gene (DNM3) and the centromere protein L gene (CENPL), were potential causes of intellectual disability and growth deficiency, respectively." (PMID 31645985, 2019).
liver cancer (1 paper, 2022). An epithelial or non-epithelial malignant neoplasm that arises from the liver. "Therefore, DNM3 is expected to be a new target for the treatment of liver cancer." (PMID 35178475, 2022).
osteoporosis (1 paper, 2025). A condition of reduced bone mass, with decreased cortical thickness and a decrease in the number and size of the trabeculae of cancellous bone (but normal chemical composition), resulting in increased fracture incidence. "Secondary analysis further confirmed the potential association of WNT2B rs3737136, CFH rs12401515, and DNM3 rs1576340 with osteoporosis-related traits, but their association with RCTs was not replicated in the present study." (PMID 40866365, 2025).
synovial sarcoma (1 paper, 2020). "Retroviral tagging of the tumor identified 15 common retroviral integration sites within the Dnm3 locus as the most frequent in 30 mouse synovial sarcomas." (PMID 32019274, 2020).
virus infection (1 paper, 2016). "The data demonstrated that Dnm1, Dnm2, and Dnm3 had significant effects on virus infection in shrimp." (PMID 27029712, 2016). "Given that Dnm1, Dnm2, and Dnm3 could be involved in virus infection at the mRNA level, we further hypothesized whether or not recombined Dnm1, Dnm2, and Dnm3 proteins affect the WSSV copies in shrimp." (PMID 27029712, 2016).
tumor (20 papers, 2015 to 2024). "The mRNA expression levels of DNM3 were negatively associated with tumor size and degree of histological differentiation (P < 0.05)." (PMID 35178475, 2022). "Emerging evidence has shown that DNM3 is associated with tumor progression." (PMID 35178475, 2022). "In terms of DNM3, its tumor suppressive function has been reported in various malignancies, including cervical and lung cancers." (PMID 38548861, 2024). "The results have shown that the positive rate of DNM3 protein expression was significantly correlated with tumor size, histological differentiation degree, and TNM stage (P < 0.05) but not with gender, age, and CEA concentration (P > 0.05)." (PMID 35178475, 2022). "Among the nine eosinophil-related genes we screened, DNM3 gene plays an important role in tumor biological progression and clinical prognosis." (PMID 35936781, 2022). "In this study, RT-qPCR and immunohistochemistry were performed, and DNM3 expression was found to be higher in adjacent non-tumor colorectal tissues than in CRC tissues." (PMID 35178475, 2022). "The expression level of DNM3 mRNA in CRC tissues was significantly correlated with tumor size and pathology classification (P < 0.05)." (PMID 35178475, 2022). "The expression level of DNM3 protein in CRC tissues was dependent on tumor size, degree of histological differentiation, and clinical stage (P < 0.05)." (PMID 35178475, 2022). "In Module 79, dynamin 3 (DNM3) which functions as a tumor suppressor in various malignancies is downregulated in H295R-PM-Ptc+ cells." (PMID 35631574, 2022). "The specific mechanism of DNM3 gene in BLCA in tumor biological progression and clinical prognosis is still unclear." (PMID 35936781, 2022). "We then further compared the DNM3 expression level in the tumor from these 23 patients with metastasis and 28 patients without metastasis." (PMID 34490234, 2021). "Dynamin 3 (DNM3) has gained increased attention ever since its potential as a tumor suppressor was reported." (PMID 34490234, 2021). "In conclusion, our data have confirmed the tumor suppressor function of DNM3 in LC and that it is mediated through suppression of the STAT3 signaling pathway." (PMID 34490234, 2021). "It has been shown that PRDX2 downregulated the expression of Dynamin 3 (DNM3), which is one member of the guanylate triphosphatases (GTPases) family and exerts as an important tumor suppressor." (PMID 32908916, 2020). "Elevated expression of DNM3 in chronic L-HES is consistent with its proposed function as a tumor suppressor." (PMID 31489115, 2019). "Dynamin 1 and 2 both enhance cancer cell proliferation, tumor invasion and metastasis, whereas dynamin 3 has tumor suppression role." (PMID 28402939, 2017). "Patients with reduced expression of dynamin 3 in tumor tissues exhibited worse prognosis with decreased disease specific survival compared to patients without decreased expression." (PMID 28402939, 2017). "Similarly, DNM3 is found to play a tumor suppressive role in both colon and cervical cancers by regulating the activities of the MMP family." (PMID 35178475, 2022). "High tumor volume indicated a low positive rate of DNM3 protein expression." (PMID 35178475, 2022). "In addition to DNM3 gene, the research of other 8 eosinophil-related genes in the tumor also made gratifying progress in recent years." (PMID 35936781, 2022). "Similarly, knowdown of DNM3 also promotes BEAS-2B cell growth, indicating the tumor-suppressive role of DNM3." (PMID 34490234, 2021). "The patients with tumor metastasis had lower DNM3 mRNA levels, suggesting that the low expression of DNM3 might also contribute to metastasis of the tumor." (PMID 34490234, 2021). "In summary, our data revealed that DNM3 could be a promising clinical marker for CRC patients, monitoring the expression of DNM3 may be helpful in predicting the tumor size, TNM stage, and histological differentiation degree of CRC." (PMID 35178475, 2022).
tumor (continued). "In terms of cancer metastasis, our results showed that CZT treatment also reduced the tumor metastasis regardless of the status of DNM3." (PMID 34490234, 2021). "No aberrant expression of DNM3 was obtained in HCC tumor tissue." (PMID 25861255, 2015). "However, the activity of DNM3 in LC is still not yet understood, and its precise function as a tumor suppressor remains unclear." (PMID 34490234, 2021). "The expression level of DNM3 mRNA in CRC tissues was independent of sex, age, clinical stage, portal vein tumor thrombus, and CEA concentration (P > 0.05) and significantly correlated with tumor size and pathology classification (P < 0.05)." (PMID 35178475, 2022). "The expression level of DNM3 protein in CRC tissues was dependent on tumor size, degree of histological differentiation, and clinical stage (P < 0.05) but not on sex, age, portal vein tumor thrombus, and CEA concentration (P > 0.05)." (PMID 35178475, 2022).
cancer (12 papers, 2015 to 2024). A tumor composed of atypical neoplastic, often pleomorphic cells that invade other tissues. "DNM3 was found being hypermethylated in cancer tissue compared with adjacent normal tissue, and this was associated with decreased expression of DNM3 in cancerous tissue." (PMID 28402939, 2017). "Another protein regulating microtubular and vesicular transport that could cause cancer cell progression was dynamin 3 (DNM3); the expression of DNM3 was also increased." (PMID 37834191, 2023). "As a result, these findings confirmed that miR-23a-3p targeted to DNM3 with negative regulation, the inhibition of DNM3 expedited cancer cell proliferation, migration and invasion." (PMID 35200104, 2022). "DNM3 plays an inhibitory role in various malignant tumors in humans." (PMID 36670743, 2023). "The present study detected DNM3 in CRC tissue samples and tissues adjacent to carcinoma specimens and examined its expression and clinicopathological characteristics." (PMID 35178475, 2022).
infection (2 papers, 2014 to 2015). The state of being infected such as from the introduction of a foreign agent such as serum, vaccine, antigenic substance or organism. "We found that the knock-down of four genes (DNM3, IDH3G, EPS15 and ATP6AP1) significantly inhibits HIV-1 replication, especially at later time-points (from four to seven days post-infection)." (PMID 25496667, 2014). "Thus, while Eps15, dynamin-1, dynamin-2, dynamin-3, and clathrin heavy chain siRNAs inhibited HMPV entry and diminished infection, cells that did become infected exhibited normal amounts of surface F protein." (PMID 26629703, 2015).
myopathy (1 paper, 2022). A disease of the muscle in which the muscle fibers do not function properly. "Forty-six candidate genes are prioritized by multiple approaches (42 for LST and 6 for MVPA; 2 overlap) and point to endocytosis (CNIH2, RAB1B, KLC2, PACS1, REPS1, DNM3, EXOC4), locomotion (CADM2, KLC2) and myopathy (MLF2, HERC1, KLC2, SIL1) as relevant pathways." (PMID 36071172, 2022).
neurodegenerative disease (1 paper, 2020). A disorder of the central nervous system characterized by gradual and progressive loss of neural tissue and neurologic function. "In this study, exogenous GalCer significantly increased expression levels of Dnm3 and Atp6v0a1 in male Cln3Δex7/8 mouse brain, suggesting a new avenue for study and treatment of neurodegenerative diseases." (PMID 33006978, 2020).
DNM3 also shares sentences with these, for which no sentence is quoted: colon cancer (2 papers); lung carcinoma (2); non-small cell lung carcinoma (2); T-cell lymphoma (2); abdominal aortic aneurysm (1); autoimmune disease (1); Hypertension (1); Intellectual disability (1); microcephaly (1); neuroblastoma (1); Parkinsonism (1); psoriasis (1); psychiatric diseases (1); Right ventricular cardiomyopathy (1); spina bifida (1).